BRCA1 (BRCA1 DNA repair associated)
Diseases named in the same sentence as BRCA1 in open-access papers (continued):
Sharing a sentence is not in itself a finding about the gene and the disease.
breast cancer (continued). "In addition two fibroblast cultures, the breast cancer cell-line HCC1937 and its corresponding B-lymphoblastoid cell line (heterozygous for mutation BRCA1 5382insC) and an epithelial ovarian cancer cell line (A2780) were studied." (PMID 11506493, 2001). "Previously, we had identified 10 patients with BRCA1 germline mutations in a hospital-based series of 642 breast cancer patients not selected for age or family history." (PMID 11720473, 2001). "In conclusion, the high prevalence of AI at BRCA1 in BRCA2 mutation tumours and vice versa suggests that somatic events occurring at the other breast cancer susceptibility gene locus may be selected in the cancer development." (PMID 11710835, 2001). "Thus far, studies investigating the differences in tumour characteristics between breast cancer in BRCA1-carriers and other patients, have focused on highly selected groups of patients, potentially limiting the conclusions that can be drawn." (PMID 11720473, 2001). "The prevalence of disease-related BRCA1 mutations was investigated in 642 Dutch breast cancer patients not selected for family history or age at diagnosis." (PMID 10952774, 2000). "Therefore, this study indicates that deletions within the β-promoter region of BRCA1 are an uncommon event in familial breast cancer." (PMID 10070866, 1999). "Further studies of breast cancer cases, particularly among BRCA1 gene carriers and their families, could improve our understanding of this effect." (PMID 7669588, 1995). "We utilized the K14-Cre Brca1f/fTp53f/f mouse model to investigate whether a pulse of PARP inhibitor (PARPi) ± an AKT inhibitor (AKTi) can prevent Brca1-related breast cancer." (PMID 41545354, 2026). "Using a transgenic mouse model where accumulated R-loops were removed in BRCA1-deficient mouse mammary epithelium through RNaseH1 overexpression, they demonstrated that R-loop removal did not influence the overall incidence of spontaneous BRCA1-associated mammary tumors." (PMID 40629041, 2025). "CHEK2 germline pathogenic variants have generally been associated with a moderate increased risk of breast cancer during life in BRCA1/2 negative patients, although an increased risk for syndromic familial non-medullary thyroid carcinomas has also been suggested." (PMID 40448797, 2025). "In breast cancer, the phase III OlympiAD and EMBRACA trials demonstrated significantly improved progression-free survival with olaparib and talazoparib, respectively, compared to standard chemotherapy in patients with HER2-negative, germline BRCA1/2-mutated metastatic disease." (PMID 41487567, 2025). "Therefore, the inhibition of PARP using synthetic killing agents could be advanced as a novel targeted therapy for breast cancer patients with dysfunctional BRCA1." (PMID 41155174, 2025). "Moreover, treatment modalities have improved breast cancer-specific survival for BRCA1/2-related breast cancer over the past several years, with the most recent addition to treatment being the use of poly adenosine diphosphate [ADP]-ribose polymerase [PARP] inhibitors." (PMID 40427184, 2025).
breast cancer (continued). "For example, previvors with a P/LP in the BRCA1 gene have up to a 72 % lifetime breast cancer risk and up to a 44 % lifetime ovarian cancer risk; however, previvors with a P/LP in the BRCA2 gene have up to a 69 % lifetime breast cancer risk and a 17 % lifetime ovarian cancer risk." (PMID 40485758, 2025). "These significant findings not only elucidate the specific regulatory mechanisms of BRCA1/2 mutations on the breast TME but also provide a solid theoretical and experimental foundation for developing precision-targeted therapies for BRCA1/2 mutation-associated breast cancer." (PMID 40867511, 2025). "Based on this preclinical and clinical data, we hypothesized that combination therapy with a dual mTOR/pan-PI3 K inhibitor, gedatolisib, and the PARPi, talazoparib, may be effective in breast cancer patients with a gBRCA1/2 m and in patients with BRCA1/2-wildtype TNBC." (PMID 40471518, 2025). "However, a ruthenium-derived glutathione transferase (GSTP-1) inhibitor, combined with olaparib, dramatically reduced the expression of the BRCA1 protein as well as the inhibition of BRCA1 replication in triple-negative BRCA1 wild-type MDA-MB-231 breast cancer cells." (PMID 41155174, 2025). "The synthetic lethal interaction between PARP inhibition and BRCA1/2 mutations formed the basis for the approval of PARP inhibitors, such as Olaparib and Talazoparib, as monotherapies for patients with loss-of-function germline BRCA-mutated HER2-negative breast cancer." (PMID 40669753, 2025). "Finally, BRCA1/2 mutation status was not collected, preventing identification of participants with hereditary breast cancer." (PMID 41419649, 2025). "Additionally, none of the studies included in this review reported BRCA1 or BRCA2 gene expression or genetic screening for breast cancer risk." (PMID 40427149, 2025). "Individuals who inherit the BRCA1 mutations confront a lifetime breast cancer risk of 65%–80% and an ovarian cancer risk of 37%–62%, whereas BRCA2 mutation carriers face a 45%–85% chance of breast cancer and a 11%–23% chance of ovarian cancer over their lifetimes." (PMID 40904409, 2025). "Further exploration into the association between breast cancer and BCAC may be of relevance, given that 2 of 11 BCAC patients in this study had LoF BRCA1 germline variants and previous studies have suggested a higher risk for breast cancer in patients with SGTs." (PMID 40389436, 2025). "Based on the limited literature from women with high familial risk or PV in BRCA1/2, exogenous hormones are not contraindicated in unaffected women, but patients with previous breast cancer (especially hormone receptor positive cancer) are advised against exogenous hormone use." (PMID 40317347, 2025). "Additionally, BRCA1/2 PV carriers may exhibit higher Oncotype DX recurrence scores, reflecting the high-grade nature of BRCA-associated breast cancer." (PMID 40405286, 2025). "However, most ovarian and breast cancers harbor wild-type (WT) BRCA1/2, limiting PARPi eligibility." (PMID 40299557, 2025). "This cohort study analyzed data from a large cohort of women with a diagnosis of breast cancer regardless of age, and we identified pathogenic or likely pathogenic variants in BRCA1 and BRCA2 in 4.4% of Asian patients, 8.1% of African American or Black patients, and 4.8% of White patients." (PMID 40952741, 2025). "For example, the inclusion of genetic markers, such as BRCA1 and BRCA2, may improve breast cancer risk prediction but may be unfeasible to deploy in population-wide screening programs due to costs, lab-related analysis burden, ethical concerns, and time delays." (PMID 41146041, 2025). "Of note, when we analysed the ENCODE data of gene promoters in MCF7 breast cancer cells that also bind BRCA2 (BRCA1 antibody is not reported in the ENCODE database) and Kaiso, we identified a generous list of genes, though fewer than co-bind gene promoters in HCT116 cells." (PMID 40460875, 2025).
breast cancer (continued). "Notably, 14% (3/21) of the identified breast cancer affected BRCA1/2 carriers and 25% (4/16) of the PALB2 carriers were diagnosed with another cancer by the time of last follow-up, and four of those were in the female reproductive system (uterus, ovaries, and two cervical cancers)." (PMID 40009290, 2025). "The amplification provides further support for the role in general oncogenic process of SMYD3, which may be independent of BRCA1 mutations, as such mutations are only identified in a small fraction (2–4%) of human breast cancers." (PMID 40157910, 2025). "There are limited prospective data on whether established risk factors modify breast cancer risk in women with pathogenic variants (PV) in BRCA1/2 and virtually no risk modification data for ATM, CHEK2, or PALB2." (PMID 40298171, 2025). "Furthermore, other families with a high likelihood of a mutation do not harbor a known pathogenic variant, demonstrating that much of the genetic contribution to breast cancer development has yet to be characterized; demonstrating the importance of multi‐gene panel testing beyond just BRCA1/2." (PMID 39907309, 2025). "In BC, triple-negative breast cancer (TNBC) is most common, emphasizing the need for regular screening and risk-reducing strategies for women with BRCA1 mutations." (PMID 40710012, 2025). "The possibility of developing breast cancer can be increased by various genetic or non-genetic factors, like the presence of mutations in breast cancer susceptibility one and two genes (BRCA1 and BRCA2), smoke, obesity, or prolonged exposure to estrogen and progesterone hormones." (PMID 40951838, 2025). "Breast cancer is associated with various modifiable risk factors –such as alcohol, tobacco consumption, or obesity, and non-modifiable risk factors –such as inherited gene mutation (e.g., BRCA 1 and /2, BRCA1 and 2 DNA repair associated), age, and family history of breast cancer." (PMID 39235717, 2025). "In this analysis of women with a BRCA1 or BRCA2 mutation, we explored whether there was an association between infertility per se, as well as the treatment of infertility, and the risk of developing breast cancer." (PMID 41214587, 2025). "BRCA1/2 and PALB2 mutations were found in 5%–6% of patients with PDAC who were unselected for mutational status, whereas higher rates of 5%–19% were found in the high‐risk populations, such as Ashkenazi Jews and those with family histories of pancreatic, ovarian, or breast cancer." (PMID 41473825, 2025). "The increased breast cancer risk after long-term use, especially before the first child that was observed in the retrospective results were not supported by the prospective analyses, neither for BRCA1-pV carriers nor for those with pV in the BRCA2 gene." (PMID 39259360, 2024). "In addition, a reduced ovarian reserve is associated with pathogenic variants in BRCA1 and thus earlier natural menopause might cause the chosen point of time for RRBSO to be too late for a reduction in breast cancer risk by hormonal deprivation." (PMID 38892081, 2024). "Additionally, mutations in certain genes, whether inherited or acquired, such as BRCA1 and BRCA2 (breast cancer susceptibility genes 1 and 2), can lead to the development of BC." (PMID 39598531, 2024). "However, women diagnosed with breast cancer have an elevated risk of a secondary tumor, and it seems reasonable to test all TNBC and HGSOC for tissue methylation and offer WBC BRCA1 methylation testing to women diagnosed with a BRCA1 methylated TNBC or HGSOC tumor." (PMID 40225940, 2024). "Furthermore, mutations in BRCA1 and BRCA2 genes are responsible for 5–10% of breast cancer cases." (PMID 39125744, 2024).
breast cancer (continued). "The most prevalent and significant susceptibility gene of BC is the breast cancer susceptibility gene (BRCA), which includes BRCA1 and BRCA2." (PMID 38424620, 2024). "Given the elevated lifetime risk, many female BRCA1/2 and PALB2 germline pathogenic variant carriers (herein referred to as “carriers”) may wish to consider risk-reducing mastectomy (RRM) in order to prevent the development of breast cancer." (PMID 38248108, 2024). "Loss-of-function mutations in the breast cancer (BC) susceptibility genes 1 and 2 (BRCA1 and BRCA2; BRCA) are associated with an increased risk of developing BC." (PMID 38112922, 2024). "However, the impact of BRCA1/2 mutations on OS during chemotherapy varies across cancer types, with no discernible effect in breast cancer (BC)." (PMID 38809921, 2024). "However, breast cancer may occur if the suppressive function of the BRCA1/COBRA1 complex is attenuated and abnormal mammary cell proliferation (hyperplasia) occurs owing to over-mobilization of BRCA1 to DSBs for HRR." (PMID 38718394, 2024). "Eleven patients with a high risk of genetic predisposition (e.g., early onset breast cancer or a strong family history of cancer) underwent germline genetic testing as per guidelines; however, none were found to carry germline mutations, including BRCA1/2." (PMID 39335094, 2024). "Methods and Results: We enrolled 396 female patients, who underwent implant-based breast reconstruction, using definitive mammary implants or breast tissue expanders, with or without ADM (acellular dermal matrix), both for breast cancer and risk-reducing surgery in BRCA1/2 patients." (PMID 39001499, 2024). "Additionally, homologous recombination deficiency scores have been found to correlate strongly with BRCA1/2 deficiency, regardless of breast cancer subtype." (PMID 39273190, 2024). "Furthermore, DDR PVs are widely used as specific diagnostic markers for cancer risk prediction, e.g., BRCA1 PVs are often used as the markers to predict breast cancer risk and guide cancer treatment, e.g., as the indicator for using PARP inhibitors (PARPi) to treat breast cancer with BRCA1 PVs." (PMID 38575974, 2024). "Similarly, the level of Tnfsf11 and Tnfrsf11a encoding respectively for the secreted factor RANKL and its receptor, RANK, involved in the oncogenesis of Brca1 mutation-driven breast cancer, was not altered in the absence of Itgα6." (PMID 38835038, 2024). "Molecular and histological factors, including PAM50 classification, estrogen receptor α (ERα), breast cancer type 1 susceptibility protein (BRCA1), progesterone receptor (PR), and HER2 expression, contribute to intricate BC subtyping." (PMID 38589728, 2024). "Therefore, women who are considered high risk due to non-modifiable factors, such as BRCA1/2 mutations or a strong family history of breast cancer, are in need of alternative prevention procedures." (PMID 38254741, 2024). "An increase in breast cancer risk in BRCA1/2-pV carriers can therefore not be ruled out." (PMID 39259360, 2024). "The clinico-pathological databases analysis showed that HER2 upregulation and PR downregulation were associated with high CHRNA6 expression, and BRCA1/2 mutation was associated with low CHRNA6 expression, suggesting that CHRNA6 may be a potential diagnostic biomarker in breast cancer." (PMID 38291367, 2024). "Collectively, our studies identify a previously unexplored role for FLT1 signaling in driving PARPi resistance in BRCA1/2-mutant breast cancers and suggest that pharmacological inactivation of FLT1 could greatly enhance the efficacy of PARPi treatment in patients." (PMID 38956205, 2024). "HMECs were screened for differences in viscoelastic phenotypes across six primary strains: three from average‐risk women (aged 33–40 years) without any known breast cancer‐causing germline mutations, and three from high‐risk women (aged 24–35 years) with BRCA1 germline mutations." (PMID 39308179, 2024).
breast cancer (continued). "However, PEMT gene methylation does not correlate with prognoses in patients with BRCA1-mutated breast cancer." (PMID 39409074, 2024). "In this cohort study, although women with breast cancer and pathogenic BRCA1/2 variants treated with breast-conserving therapy had above-average risks of ipsilateral and contralateral breast cancer events, most did not have another cancer event and remained bilateral mastectomy free." (PMID 38916888, 2024). "Data on the effects of HRT on breast cancer risk in BRCA1/2-pV carriers without RRSO are limited." (PMID 39259360, 2024). "In other breast cancer patient cohorts with no selection bias, the rate of detection of variants in BRCA1/2 was approximately 4–5%, while the cumulative variant detection rate achieved through multigene panel analysis ranged from 6% to 9%, representing a 1.4- to 2-fold augmentation." (PMID 38397209, 2024). "For example, our study lacked information on genetic history or predisposition for breast cancer (e.g., BRCA1/BRCA2), though this would likely not be related to air pollution exposure, and therefore may not be a true confounder." (PMID 38630334, 2024). "In addition, the development of ER-alpha negative breast cancer has been reported to be a predictor of BRCA1 mutation status in patients." (PMID 38672654, 2024). "Additionally, 18.1% of breast cancer patients with BRCA1/2 variants had menarche ages younger than 13 years, compared to only 12.2% of breast cancer patients with non-BRCA variants." (PMID 38167124, 2024). "To investigate whether MBC and FBC risk might be at least in part due to different genes, we then examined their mutability in a population of high-risk breast cancer women without BRCA1/BRCA2/PALB2 PV/LPV detected on the same 585-gene panel analysis." (PMID 37762649, 2023). "To test this hypothesis, we used breast cancer samples and the BRCA1 and BRCA2 genes as a model." (PMID 37046838, 2023). "This study evaluated the effect of age at breast cancer diagnosis and cancer family history on the risk of carrying a PV in breast cancer susceptibility genes routinely included in breast cancer predisposition multi-gene panels, ATM, BRCA1, BRCA2, CHEK2, and PALB2." (PMID 37084156, 2023). "Another meta-analysis included three cohort studies for 1100 healthy women with BRCA1 and BRCA2 P/LP germline variants who underwent risk-reducing bilateral salpingo-oophorectomy before the onset of natural menopause to assess the association between breast cancer incidence and HRT." (PMID 37628558, 2023). "From 57 participating centers in seven countries examining 6052 women, it was reported that in the 15-year period after breast cancer diagnosis, the risk of diabetes doubled among BRCA1/2 carriers compared with carriers without cancer, especially for women with high BMI." (PMID 37510134, 2023). "Germline testing for breast cancer should also include the PALB2 gene, considering the frequency of pathogenic defects in the general population and because PALB2 heterozygotes should be considered for the same therapeutic regimens and clinical trials as those for BRCA1 and BRCA2 carriers." (PMID 37239058, 2023). "Thus, stimulation of HR pathway in olaparib-treated ZNF251KD BRCA1-mutated breast cancer cells did not play a key role in the resistance." (PMID 37066268, 2023). "Previous studies have shown that decision-making regarding options for coping with increased risk of breast cancer is strongly influenced by whether women know they are carriers of P/LP variants in BRCA1/2 or not." (PMID 36971799, 2023).